ALB (albumin)
Diseases named in the same sentence as ALB in open-access papers (continued):
Sharing a sentence is not in itself a finding about the gene and the disease.
diabetic ketoacidosis (9 papers, 2021 to 2026). The metabolic condition resulted from uncontrolled diabetes mellitus, in which the shift of acid-base status of the body toward the acid side because of loss of base or retention of acids other than carbonic acid is accompanied by the accumulation of ketone bodies in body tissues and fluids. "Low ALB concentration is correlated with the higher risk of mortality in patients with diabetic ketoacidosis." (PMID 38128055, 2023). "This study aimed to investigate the association between blood urea nitrogen to serum albumin ratio (BAR) and the risk of in-hospital mortality in patients with diabetic ketoacidosis." (PMID 38994011, 2024). "RDW/albumin (ALB) ratio is a new combined parameter that can predict mortality in patients undergoing burn surgery, and patients with diabetic ketoacidosis." (PMID 35658957, 2022).
Dysphagia (9 papers, 2019 to 2025). "Our study found that the CRP to ALB ratio is positively correlated with mortality in dysphagia patients, which can serve as a practical tool for evaluating patient outcomes in clinical practice." (PMID 38993239, 2024). "The C-reactive protein/albumin ratio was positively related to mortality in Japan older people with dysphagia patients." (PMID 38993239, 2024).
endometritis (9 papers, 2016 to 2025). An acute or chronic, usually bacterial infectious process affecting the endometrium. "The findings also present strong evidence of significant biochemical and hormonal changes linked to endometritis in Egyptian buffalo cows, specifically in relation to blood sugar, cholesterol, total protein albumin, urea, estrogen, progesterone, FSH, LH, T4, PGF2α, calcium, iron, and selenium." (PMID 39195794, 2024). "When compared to healthy buffaloes, endometritis-affected buffaloes have significantly lower serum albumin concentrations because endometritis is an acute inflammation of the endometrium." (PMID 39195794, 2024). "The levels of albumin, a negative APP, in cows with endometritis (3.4±0.1 g/dl) were significantly lower than in healthy cows (3.6±0.1 g/dl)." (PMID 27847413, 2016).
Hyperammonemia (9 papers, 2008 to 2026). An increased concentration of ammonia in the blood. "In fact, the multivariate models using the cutoff values for albumin (≤ 3.5 g/dL) and ammonia (≥ 80 μg/dL) showed that hyperammonemia had weak ability to identify CHE and OHE." (PMID 36449492, 2022). "In this same review, low albumin and hyperammonemia were noted." (PMID 41561891, 2026). "Albumin plasma levels correlate with the TAX and with the hyperammonemia in portosystemic shunted rats." (PMID 18251997, 2008).
Hypercalciuria (9 papers, 2021 to 2025). "The link between hypercalciuria and serum albumin-corrected calcium underlines the importance of careful monitoring of this electrolyte." (PMID 38027217, 2023). "Complementary evaluation revealed protein/creatinine ratio of 1.9 g/g and albumin/creatinine ratio of 0.5 g/g, hypercalciuria and medullary nephrocalcinosis." (PMID 36688186, 2023). "Furthermore, serum albumin-adjusted calcium levels that are persistently outside the normal range and hypercalciuria are additional indications for PTH replacement therapy." (PMID 40794165, 2025). "However, in our study, only the baseline body surface and serum albumin level were predictive of hypercalciuria occurrence." (PMID 34266398, 2021). "The addition of albumin (5 mg/mL), glucose (10 mg/mL), calcium chloride (3 mg/mL) or acetone (7.9 mg/mL) to simulate significant albuminuria, glucosuria, hypercalciuria or ketonuria resulted in no significant change in the measured urinary sGAG concentration." (PMID 37629312, 2023).
hypersplenism (9 papers, 2015 to 2025). Overactive functioning of the spleen, resulting in excessive destruction of blood cells. "Serum albumin, cholesterol, calcium, and potassium levels were within normal values in both groups but were significantly lower in the hypersplenism than in the asplenia/hyposplenism group (p = 0.05)." (PMID 36105295, 2022). "Thus, patients with hypersplenism had lower albumin levels and their HBV-DNA copies was mostly negative." (PMID 37021093, 2023).
hyperthyroxinemia (9 papers, 2017 to 2024). Abnormally elevated thyroxine level in the blood. "A different variant at this position in albumin (Arg218Pro) binds steroid as well as iodothyronines, causing artefactual hyperthyroxinemia and hypercortisolemia." (PMID 37988295, 2024). "Knowing that FDH is commonly caused by a restricted repertoire of genetic variants, we sequenced ALB and identified the most common causal variant (Arg218His) in her case, as well as in her sibling with hyperthyroxinemia." (PMID 37988295, 2024). "Familial dysalbuminemic hyperthyroxinemia (FDH) is an autosomal dominant disorder caused by mutations in the albumin gene (ALB) that results in an abnormally increased affinity of albumin for serum thyroxine (T4)." (PMID 37853391, 2023). "A case report of familial dysalbuminemic hyperthyroxinemia revealed that the patient showed extremely high serum free thyroxine concentration due to p.R242P mutation in the ALB gene." (PMID 35982996, 2022). "Due to variants of the gene coding for albumin (ALB), Familial Dysalbuminemic Hyperthyroxinemia (FDH) is the most common cause of inherited euthyroid hyperthyroxinemia in the Caucasian population, with an estimated prevalence of 1 in 10,000 individuals." (PMID 32635414, 2020). "In two individuals with hyperthyroxinemia due to an ALB mutation (R218P) known to cause FDH, we have documented hypercortisolemia with euadrenal status and shown that this discordance is due to abnormal binding of steroid to circulating albumin." (PMID 32669045, 2020). "Family dysalbmuinemic hyperthyroxinemia (FDH) is an autosomal dominant disease characterized by euthyroid hyperthyroxinemia due to a high affinity of defective albumin for iodothyronine." (PMID 36864842, 2023). "Familial dysalbuminemic hyperthyroxinemia (FDH) is an autosomal dominant disease characterised by an abnormally increased affinity of albumin for serum thyroxine." (PMID 37853391, 2023). "In this study, we report two individuals with FDH due to R218P mutant albumin who exhibited hypercortisolemia and hyperthyroxinemia, likely due to increased binding of steroid as well as iodothyronines to mutant albumin." (PMID 32669045, 2020). "For avoiding unwanted treatment of euthyroid persons with hyperthyroxinemia or hypertriiodothyroninemia, protein sequencing and/or sequencing of the albumin gene should be performed." (PMID 29163366, 2017). "Familial dysalbuminemic hyperthyroxinemia and FDH-T3 are dominantly inherited conditions caused by genetic variants of HSA with increased affinity for thyroid hormones." (PMID 29163366, 2017). "Besides, it has been reported that elevated serum iodothyronine levels in the absence of thyrotoxicosis may exist, called familial dysalbuminemic hyperthyroxinemia (FDH) due to variants in the gene encoding albumin (ALB)." (PMID 37602950, 2023). "Familial dysalbuminemic hyperthyroxinemia (FDH), a dominantly inherited condition due to circulating mutant albumin with altered binding affinity for thyroid hormones (TH), is a recognized cause of elevated serum thyroxine (T4) in euthyroid individuals." (PMID 32669045, 2020).
hypogonadism (9 papers, 2019 to 2025). A disorder characterized by decreased function of the gonads. "A similar study showed that advancing age, low serum albumin, high total bilirubin, and prothrombin time were significantly associated with secondary hypogonadism and low testosterone values." (PMID 36814749, 2023). "Because testosterone is anabolic, a secondary objective of this study was to test the hypothesis in a small exploratory sub-study that there is an association between levels of pre-albumin and testosterone in otherwise healthy men who are being evaluated for possible adult onset hypogonadism." (PMID 30670838, 2020). "In addition, hypogonadism in advanced cancer patients may be associated with low serum albumin resulting from the depletion of body protein." (PMID 32365474, 2020). "In summary, by EOT, all patient groups in all the clinical trials showed resolution of their hypogonadism, accompanied by increased serum albumin levels and increased BMI." (PMID 35650700, 2022). "In a smaller exploratory study of 19 otherwise healthy men presenting for evaluation of possible hypogonadism, pre-albumin (a.k.a.transthyretin, a marker of anabolism) and testosterone were measured." (PMID 30670838, 2020). "It is suggested that assessment of cBT or free T (unbound to SHBG or albumin) is more appropriate than that of TT alone for diagnosing hypogonadism, particularly in the cancer setting." (PMID 31487803, 2019). "The corrected model further identified normal BMI (OR=0.383) and ALB (OR=0.866) as protective factors, while IGF-1 levels < -2 SD (OR=1.832) and hypogonadism (OR=2.990) emerged as significant risks in the uncorrected model." (PMID 40671911, 2025). "Neither measurement of SHBG and albumin, nor free-T calculation was available in patients with TT in “grey zone“ (264–300 ng/dl), which may have possibly impacted on the real prevalence of hypogonadism in the enrolled patients." (PMID 33063272, 2021).
Impaired glucose tolerance (9 papers, 2016 to 2025). An abnormal resistance to glucose, i.e., a reduction in the ability to maintain glucose levels in the blood stream within normal limits following oral or intravenous administration of glucose. "Albumin has been recently shown to be elevated in these complexes isolated from humans with impaired glucose tolerance and T2D, and clearance of these complexes would further lower albumin levels." (PMID 30774722, 2019). "HD fed mice showed increased body weight and impaired glucose tolerance, whereas pyridoxamine administration significantly improved insulin sensitivity, but not body weight, and reduced diet-induced increase in serum creatinine and urine albumin." (PMID 29214163, 2017).
infertile (9 papers, 2013 to 2025). "In this study we compared IV Human Albumin with Dopamine agonist, cabergolin in infertile patient at high-risk for OHSS in IVF\ICSI cycles." (PMID 24639705, 2013). "On the other hand, individuals in the infertile group had lower levels of high-density lipoprotein (HDL) cholesterol and albumin compared to fertile individuals." (PMID 40612439, 2025). "In the present study we seek to further characterize key components of 25OHD metabolism in infertile patients and fertile controls by measuring 25OHD, DBP, and albumin with subsequent calculation of free and bioavailable 25OHD followed by comparison of these parameters between groups." (PMID 29046816, 2017).
leprosy (9 papers, 2014 to 2024). Leprosy is a chronic infectious disease affecting primarily the skin and peripheral nervous system. "Thus, studies from diverse regions have varied results, with some reporting association between leprosy and low serum albumin and others failing to do so." (PMID 35449687, 2022). "We recommend the inclusion of BMI measurement and the assessment of hemoglobin, serum iron, serum albumin, and serum cholesterol in the initial assessment of a leprosy patient, with sequential follow-up after the initiation of treatment." (PMID 35449687, 2022). "Most leprosy patients with plantar ulcers have normal levels of serum albumin and transferrin and high CRP levels, which indicates the presence of an inflammatory process." (PMID 28866982, 2017). "In our study, most leprosy patients with plantar ulcers had normal serum levels of albumin and transferrin, but high serum CRP levels, which indicate the existence of an inflammatory process." (PMID 28866982, 2017). "We observed a reduction in albumin levels in patients with both forms of leprosy, although most of the patients had MB leprosy." (PMID 28866982, 2017). "Considering that more than 15% of leprosy patients can show elevated urine albumin excretion, urinary MCP-1 can be a useful early biomarker to identify patients at risk." (PMID 25142123, 2014). "The prevalence of stunting was not reported for leprosy but for leishmaniasis; conducting multiple discriminant analyses revealed albumin concentration and HAZ score as predictors of active and oligosymptomatic visceral leishmaniasis." (PMID 39539349, 2024).
leptospirosis (9 papers, 2007 to 2024). A contagious bacterial infection caused by spirochetes of the genus Leptospira. "In this study, we aimed to investigate the relationship of oleic acid/albumin (OA/A) molar ratio and clinical outcomes in Leptospirosis." (PMID 33732938, 2021). "During leptospirosis, patients have higher serum free fatty acid levels, decreased serum albumin, and elevated serum total bilirubin resulting from hepatic abnormalities." (PMID 33732938, 2021). "Patients testing positive for leptospirosis reported confusion (40%), and had significantly lower albumin levels." (PMID 32804954, 2020). "The relationship of oleic acid/albumin and the reestablishment to near control values was shown in preliminary studies to be an excellent parameter indicating leptospirosis patient recovery, demonstrating its potential as a prognostic biomarker factor for leptospirosis outcomes." (PMID 37512868, 2023). "Leptospirosis clinical outcome; Acute lipotoxicity; Lipidome; Oleic acid/albumin; Na/K-ATPase." (PMID 33732938, 2021). "Serum albumin levels, white blood cells counts, neutrophil percentages were significantly higher, and haemoglobin levels, and lymphocyte percentages were significantly lower in leptospirosis patients (both SL and ML) compared to DC." (PMID 27280281, 2016). "Therefore, a constant oleic acid/albumin ratio over 0.7150 may be considered a marker leading to leptospirosis mortality." (PMID 33732938, 2021). "Patients with leptospirosis present metabolic disturbance with dyslipidemia with a rise in blood NEFA levels and OA/A and oleic + linoleic/albumin molar (OA + L/A) ratios imbalance, which correlates with the disease severity in such patients." (PMID 33732938, 2021). "Compared with the anicteric group, patients with icteric leptospirosis had significantly lower platelet count, glomerular filtration rate (GFR), and serum albumin levels." (PMID 34570814, 2021). "Elevated levels of NEFA in the bloodstream, and an imbalance between NEFA and albumin levels, added to the fact that NEFA have pro-inflammatory capability due to the activation of TLR, may explain the pro-inflammatory status of leptospirosis." (PMID 37512868, 2023). "There was no distinct pattern in serum albumin levels between leptospirosis groups during the studied period." (PMID 33732938, 2021). "Through a prospective observational cohort study employing high-performance liquid chromatography (HPLC) we sequentially determined serum concentrations of nonesterified fatty acids (NEFA) and albumin in twenty-eight patients with severe leptospirosis since their hospital admission." (PMID 33732938, 2021).
Liver abscess (9 papers, 2016 to 2025). A circumscribed area of pus or necrotic debris in the liver. "Reduced ALB and GLOB concentrations in the blood of the EA fed steer is indicative of impaired liver function and has also been associated with the presence of liver abscess." (PMID 38442241, 2024). "We noted that the level of inflammatory markers was still high, while that of albumin was statistically and significantly lower in patients with large liver abscesses." (PMID 33573593, 2021). "The large liver abscess group had lower hemoglobin and albumin levels and higher aspartate aminotransferase and alanine aminotransferase (ALT) levels." (PMID 33573593, 2021). "The most common presentation of a liver abscess is fever, chills, and right upper quadrant pain with laboratory investigations showing low albumin, elevated alkaline phosphatase, and leukocytosis." (PMID 27540556, 2016).
malabsorption syndrome (9 papers, 2014 to 2026). A syndrome resulting from the inadequate absorption of nutrients in the small intestine. "Immunoglobulin and lymphocyte loss frequently accompanies protein loss, such as albumin, lipoprotein, fibrinogen, transferrin, and ceruloplasmin, through the intestinal tract, in patients with malabsorption syndrome." (PMID 37744114, 2021). "According to the Merck veterinary manual: malabsorption syndrome in small animals and low plasma albumin levels may indicate lower protein absorption." (PMID 24750587, 2014).
Neonatal sepsis (9 papers, 2019 to 2026). Systemic inflammatory response to infection in newborn babies. "This study aimed to assess the prognostic relevance of the lactate dehydrogenase (LDH)-to-albumin ratio (LAR) in neonatal sepsis." (PMID 40307261, 2025). "Variables with P‐value < 0.05 in univariate analysis, including BIND score, TSB peak value, B/A, albumin level, neonatal sepsis, and abnormal AABR, were selected for bivariate logistic regression analysis." (PMID 32495505, 2020). "Univariate analysis for BIND score, TSB peak value, bilirubin–albumin ratio (B/A), albumin level, abnormal AABR, and neonatal sepsis was performed to elucidate the association with adverse outcomes." (PMID 32495505, 2020). "Hypoalbuminemia and hypotension during neonatal sepsis are frequently tackled with albumin infusion, in the attempt to raise intravascular oncotic pressure despite the absence of scientific evidence, or evidence-based therapeutic individualization." (PMID 31456998, 2019). "Moreover, ischemia modified albumin cloud be an effective diagnosis marker of neonatal sepsis." (PMID 36465642, 2022). "Various other ratios are being used in the diagnosis of neonatal sepsis, which includes CRP/albumin ratio, neutrophil–lymphocyte ratio, and platelet to lymphocyte ratio." (PMID 34676267, 2021). "Recently, CRP/albumin ratio is used as a potential marker for gram-negative bacteremia in late-onset neonatal sepsis." (PMID 34676267, 2021). "Additionally, we also evaluated the ability of PCT, ALB and CRP to predict neonatal sepsis." (PMID 36908271, 2023).
non-alcoholic steatohepatitis (9 papers, 2019 to 2026). "Several factors were associated with non-alcoholic steatohepatitis, including aspartate and alanine aminotransferases (p < 0.001 and p = 0.006, respectively), gamma-glutamyl transpeptidase (p < 0.001), triglycerides (p < 0.001), serum albumin (p < 0.001)." (PMID 36983160, 2023). "In addition, decreased serum albumin, erythrocyte, hemoglobin, ALT, AST, and TC were strongly associated with aging and could reflect the inflammation, metabolic demand and several pathological conditions, including NAFLD, non-alcoholic steatohepatitis, fibrosis and hepatocyte carcinoma." (PMID 36438212, 2022). "Albumin-Bilirubin score (ALBI) and PLT count-based NITs (PLNs) (Fbrosis-4 [FIB-4], ALBI-FIB-4, red cell distribution width-to-PLT ratio [RPR], liver stiffness measurement [LSM]-to-platelet ratio [LSM/PLTr], and ANTICIPATE ± non-alcoholic steatohepatitis [NASH]) were determined." (PMID 40606502, 2025).
polycystic kidney disease (9 papers, 2013 to 2025). A usually autosomal dominant and less frequently autosomal recessive genetic disorder characterized by the presence of numerous cysts in the kidneys leading to end-stage renal failure. "Low BMI (<20 kg/m2), low serum albumin level (<30 g/dl), presence of comorbidities, physical disabilities, emergency first dialysis and all primary renal diseases (compared with polycystic kidney disease) were significantly associated with higher mortality risk." (PMID 27082113, 2016). "To exclude that albumin leakage induced in GOAC by MN serum was due to an unselective response to serum from subjects affected by CKD, we exposed the chip to sera from individuals with AS, polycystic kidney disease (PKD), or FSGS." (PMID 31409793, 2019).